TUG1 (taurine up-regulated 1)
Diseases named in the same sentence as TUG1 in open-access papers (continued):
Sharing a sentence is not in itself a finding about the gene and the disease.
breast carcinoma (31 papers, 2016 to 2025). "Recent studies have shown an association between the augmented expression of TUG-1 and clinical variables in breast cancer tissues." (PMID 35132340, 2022). "The analysis of the TCGA database showed that higher expression of TUG1 was associated with better prognosis in breast cancer patients." (PMID 32190687, 2020). "Recently, differential expression of TUG1 was found in cancerous breast tissues and associated with breast cancer malignancy features." (PMID 29657297, 2017). "In breast cancer, the long non-coding RNA (lncRNA) TUG1 has emerged as a critical regulatory element through its interaction with miR-145-5p." (PMID 40758729, 2025). "The limitations of this study indeed lie in its focus on the role of Artesunate in regulating the malignant phenotypes of breast cancer cell lines through the LncRNA TUG1 target." (PMID 40758729, 2025). "In conclusion, this study demonstrates that artesunate has the potential to modulate the malignant progression of breast cancer cells through the lncRNA TUG1/miR-145-5p/HOXA5 axis, offering promising evidence for its anti-cancer effects." (PMID 40758729, 2025). "In conclusion, artesunate has the potential to modulate the malignant progression of breast cancer cells through the lncRNA TUG1/miR-145-5p/HOXA5 axis, offering promising evidence for its future application in clinical trials for breast cancer treatment." (PMID 40758729, 2025). "lncRNA taurine upregulated gene 1 (TUG1), also known as lncRNA00080, has a low expression level in breast cancer tissues and cells at a low level in breast cancer tissues and cells." (PMID 40093330, 2025). "TUG1 regulates the resistance of breast cancer cells to adriamycin by targeting binding to miR-9-5p and by acting on the downstream target eIF5A2." (PMID 38339157, 2024). "Knockdown of TUG1 significantly slows down cell proliferation, cell migration, and invasion in breast cancer cell lines MDA-MB-231 and MDA-MB-436." (PMID 39479021, 2024). "Overexpression of TUG1 significantly inhibited breast cancer cell proliferation by leading to cell cycle arrest, while TUG1 knockdown promoted cell cycle progression by increasing the CCND1-CDK4 complexes expression." (PMID 38546402, 2024). "The relative expression of different lncRNAs studied such as ANRIL (3.83 fold), TUG-1 (7.64 fold), UCA-1 (7.82 fold), and HIT (3.46 fold) and their association with clinical and pathological characteristics among the breast cancer patients (, –5) was obtained." (PMID 35132340, 2022). "In breast cancer cell lines, although TUG1 expression profile were similar to that seen in patients, the difference was not significant (p = 0.39) (Figure A1)." (PMID 29657297, 2017). "This oncogenic function of TUG1 has also been demonstrated in breast cancer, gastric cancer, and gallbladder carcinoma." (PMID 29371936, 2017). "Based on a review of previous experiments, it was hypothesized that the inhibitory effects of Artesunate on breast cancer cells occur through its regulation of lncRNA TUG1." (PMID 40758729, 2025). "Therefore, this study aims to investigate the potential role of the lncRNA TUG1/miR-145-5p/HOXA5 signaling pathway in mediating the anticancer effects of artesunate in breast cancer." (PMID 40758729, 2025). "Given the established inhibitory effects of artesunate on breast cancer, we hypothesize that its anticancer activity may be mediated through down-regulation of lncRNA TUG1, subsequent activation of miR-145-5p, and inhibition of the HOXA5/WNT signaling axis." (PMID 40758729, 2025). "In breast cancer, lncRNA taurine-upregulated gene 1 (TUG1) was down-regulated." (PMID 38546402, 2024).
breast carcinoma (continued). "In vitro, overexpressing TUG1 markedly inhibits cell proliferation by inducing cell cycle arrest and apoptosis in breast cancer cells, while silencing TUG1 leads to increased cell growth by promoting cell cycle progression and altering the expression of cyclinD1 and CDK4." (PMID 39479021, 2024). "Interestingly, the lncRNA taurine upregulated gene 1 (TUG1) was found to negatively regulate miR-9 expression but positively regulate the expression of MTHFD2 in breast cancer cells." (PMID 37147729, 2023). "Similarly, the metformin-regulated expression of MALAT1, HOTAIR, and TUG1 was reported to be upregulated in breast cancer cells." (PMID 38053839, 2023). "lncRNA TUG1 promoted the proliferation of MCF-7 breast cancer cells by inhibiting microRNA-9." (PMID 34039257, 2021). "TUG1 is known to promote cell proliferation in breast cancer." (PMID 29715309, 2018). "The involvement of TUG1 in breast cancer is still controversial." (PMID 29657297, 2017). "Whether HOXA5 promotes breast cancer progression by enhancing glycolysis suggests that, based on molecular docking experiments, Artesunate could inhibit the aggravation of malignant phenotypes through lncRNA TUG1-mediated glycolysis suppression." (PMID 40758729, 2025). "However, the exact molecular control mechanism of TUG1 in breast cancer progression remains unclear." (PMID 35132340, 2022). "lncRNA TUG1 affected proliferation by regulating wnt/β-catenin signal pathway, miR-384, miR-498, miR-29c, miR-299-3p, or microRNA-9, in oral squamous cell carcinoma, nasopharyngeal carcinoma,esophageal squamous cell carcinoma, pancreatic cancer, breast cancer, respectively." (PMID 34039257, 2021). "Although this is evidence of a potential role in breast cancer, TUG1 expression could not be associated with different subtypes, possibly due to the small number of samples analyzed." (PMID 29657297, 2017). "Increased ANRIL (3.83-fold), TUG1 (7.64-fold), UCA1 (7.82-fold), and HIT (3.31-fold) expressions were observed in breast cancer patients compared to healthy controls." (PMID 35132340, 2022). "Survival analysis of breast cancer patients were performed based on low (≤1 fold) or high (>1 fold) expression of lnc ANRIL, TUG1, UCA1, and HIT RNAs." (PMID 35132340, 2022). "In this study, we aimed to determine the expression of ANRIL, TUG1, UCA1, and HIT lncRNAs in breast cancer patients." (PMID 35132340, 2022). "For example, MALAT1, HOTAIR, lincRNAp21, GAS5, TUG1, and ncRNA-CCND1 were identified in EVs derived from human cervical and breast carcinomas." (PMID 35250537, 2022). "Latterly, taurine upregulated gene 1 (TUG1) expression was proved to be enormously elevated in most cancers, for instance prostate cancer, breast cancer, endometrial cancer and cervical cancer." (PMID 31920462, 2020). "TUG1, regulating M7 of CC set and M2, M5, and M8 of PFC set, was reported to be a tumor suppressor in breast cancer and high correlations were found between ASD prevalence and the incidence of in situ breast cancer." (PMID 31649562, 2019). "However, in another study, TUG1 expression is significantly decreased in TNBC cell lines compared with normal breast epithelial cell lines and cell lines of other subtypes of breast cancer." (PMID 39479021, 2024). "Since the survival were evaluated for ANRIL, TUG1, and HIT RNAs among the breast cancer patients." (PMID 35132340, 2022). "In the current study, we analyzed the expression profiles of TUG1, ANRIL, UCA1, and HIT lncRNAs in breast cancer patients and investigated the differential expression of four pairs of lncRNA to determine their oncogenic roles and associations with clinical and pathological features." (PMID 35132340, 2022). "High expression of TUG1 in breast cancer tissues compared to adjacent tissues was not confirmed in the present study; herein TUG1 expression was quite similar in tumor and control samples." (PMID 29657297, 2017).
breast carcinoma (continued). "The transcript level of TUG1 in breast cancer tissues was not differentially expressed when compared to adjacent non-cancerous tissue when all samples were considered (p = 0.18) nor in paired comparison analysis (p = 0.12)." (PMID 29657297, 2017). "Although this study evidenced the potential role of TUG1 in breast cancer, they failed to examine TUG1 expression in different subtypes, possibly due to the small number of samples analyzed." (PMID 29657297, 2017). "However, other studies reported a decrease in the expression of TUG1 by metformin in vascular wall cells, a decrease in the expression of HOTAIR by metformin in MDA-MB-231 breast cancer cells, and a decrease in the expression of MALAT1 by metformin in cervical cancer cells." (PMID 38053839, 2023). "We observed that the breast cancer patients have low and high expression in ANRIL, TUG1, and HIT lncRNAs and none patients who had low expression in UCA1." (PMID 35132340, 2022).
gastric cancer (31 papers, 2014 to 2023). A primary or metastatic malignant neoplasm involving the stomach. "lncRNA TUG1 promoted the proliferation and invasion of gastric cancer cells by negatively modulating miRNA-145-5p." (PMID 34039257, 2021). "lncRNA TUG1 promoted the migration, invasion and metastasis of laryngeal cancer, esophageal squamous cell cancer and gastric cancer." (PMID 34039257, 2021). "In order to verify the correlation between TUG1 and the prognosis of gastric cancer, this meta-analysis systematically integrated all published research data, so as to reveal the relationship between TUG1 and the prognostic value of gastric cancer." (PMID 33285765, 2020). "This review provided a comprehensive overview of the relationship between TUG1 and the prognosis of patients with gastric carcinoma, and offered recommendations for clinical practices or guidelines." (PMID 33285765, 2020). "TUG1 has recently been shown to express at a significantly high level and predicts the overall survival of gastric cancer patients." (PMID 29719612, 2018). "For example, lncRNA TUG1 promotes gastric cancer cells proliferation and invasion in via negatively modulating miRNA-145-5p." (PMID 29179477, 2017). "In gastric cancer, TUG1 epigenetically silencing of p57 by binding with PRC2 to regulates cell proliferation." (PMID 28069000, 2017). "In this study, we found that TUG1 is significantly increased and is correlated with outcomes in gastric cancer (GC)." (PMID 26913601, 2016). "In order to provide a basis to judge the prognosis of gastric cancer patients, the study on whether TUG1 can be used as a more sensitive molecular marker and therapeutic target for gastric cancer should be further explored." (PMID 33285765, 2020). "At the same time, the prognostic value of TUG1 expression in gastric cancer remains controversial." (PMID 33285765, 2020). "Therefore, this study attempted to explore the relationship between TUG1 and the prognosis of patients suffering from gastric carcinoma." (PMID 33285765, 2020). "TINCR was upregulated in human gastric carcinoma, and TUG1 was upregulated in many cancer tissues and cells; therefore, the increased expression of LUCAT1, TINCR, and TUG1 might not be specific to ACBP and ASLB treatments." (PMID 29156779, 2017). "The relationship between lncRNA taurine upregulated gene 1 (TUG1) and the prognosis of patients with gastric carcinoma still needs to be further explored." (PMID 33285765, 2020). "OR3A4, LOC84740, FCGR1C, and NCRNA00200 were overexpressed in gastric cancer tissues, whereas MSTO2P, LOC344595, TUG1, and TYW3 were downregulated." (PMID 26863570, 2016). "OR3A4, LOC84740, FCGR1C, and NCRNA00200 were upregulated in gastric cancer tissues, whereas MSTO2P, LOC344595, TUG1, and TYW3 were downregulated (P < 0.05)." (PMID 26863570, 2016).
lung cancer (31 papers, 2014 to 2025). A malignant neoplasm involving the lung. "Increasing reports showed that many lncRNAs including RMRP, PVT1, HOTAIR, HIT, and TUG1 showed disease-associated dysregulation in lung cancer." (PMID 30154938, 2018). "The lncRNAs controlled by MRTF–SRF signaling include Tug1 and Malat1/Neat2 (a lncRNA implicated in lung cancer cell invasion and metastasis), which are recruited by unmethylated and methylated PC2, respectively." (PMID 24732378, 2014). "We found the top 30 lncRNAs associated with lung cancers and inferred that lncRNAs TUG1, PTENP1, and UCA1 may be biomarkers of lung neoplasms, non-small–cell lung cancer, and LUAD, respectively." (PMID 35938010, 2022). "Key lncRNAs such as NEAT1, TUG1, MALAT1, HOTAIR, and GAS5 demonstrate a crucial role in lung cancer progression and serve as powerful prognostic and diagnostic biomarkers." (PMID 39201688, 2024). "Particularly, H19, NEAT1, SNHG1, and TUG1 were significantly more expressed in lung cancer patients from both AA and WA lung cancer patients compared to those without cancer." (PMID 38791954, 2024). "In lung cancer, TUG1 promotes tumor growth, metastasis, and resistance to therapy by modulating the expression of oncogenes, tumor suppressors, and signaling pathways involved in cell proliferation and survival." (PMID 39201688, 2024). "TUG1: TUG1 is a conserved lncRNA implicated in COPD pathogenesis and lung cancer progression, whose dysregulated expression correlates with disease severity and poor clinical outcomes." (PMID 39201688, 2024). "TUG1 promotes lung cancer progression by modulating epithelial-to-mesenchymal transition (EMT) and metastasis through its interaction with miRNAs and protein-coding genes involved in tumor initiation and progression." (PMID 39201688, 2024). "To date, TUG1 is found to functions in a variety of tumors, including lung cancer, HCC, breast cancer, ovarian cancer, bladder cancer, gastric cancer and colorectal cancer 115-118." (PMID 34976181, 2022). "The expression of lncRNA TUG1 in male lung cancer tissues was lower than that in the corresponding paracancerous tissue." (PMID 34039257, 2021). "LncRNAs are overexpressed in a variety of cancers, including lncRNA DGCR5 and DANCR in lung cancer, lncRNA H19 in melanoma, and lncRNA TUG1 in ovarian cancer." (PMID 34131102, 2021). "TUG1 was significantly downregulated in lung cancer tissues compared with the corresponding normal lung tissues." (PMID 32117734, 2020). "LncRNA TUG1 was expressed at low levels in lung cancer cells, which is involved in lung cancer cell growth by regulating LIMK2b via EZH2." (PMID 30925672, 2019). "For example, TUG1 was overexpressed in small cell lung cancer, and TUG1 down-regulation sensitized lung cancer cells to chemotherapeutic drugs (DDP, Adriamycin and Etoposide) by epigenetically suppressing LIM-kinase 2b (LIMK2b) expression through EZH2." (PMID 30519392, 2018). "Of note, the prognostic value of lncNA TUG1 in lung cancer was inconsistent and need to be further elucidated." (PMID 28548946, 2017). "In brief, TUG1 is a novel player in lung cancer and may be a potential marker for the management of this malignant disease." (PMID 34976181, 2022). "The difference in the role of TUG1 in NSCLS and SCLC must be clarified by expanding the included studies in the future, and the specific lung tissue and pathological type may determine the prognostic role of TUG1 in lung cancer." (PMID 33747256, 2021). "However, in non‐small cell lung cancer, TUG1 inhibits the growth of tumor cells and thus serves as a tumor suppressor." (PMID 34097717, 2021). "Investigations of TUG1 in lung cancer were previously reported." (PMID 31532756, 2019).
lung cancer (continued). "Current insights into the molecular systems of lncRNA-miRNA-mRNA regulatory interactions and implications in lung cancer allow a hypothesis that TUG1 may be involved in the regulatory network of mRNA via ceRNA mediated miRNA evasion." (PMID 31532756, 2019). "The dysregulation of TUG1 is known to affect genes related to the growth and migration of several types of cancers, such as human nonsmall cell lung cancer 19, osteosarcoma 20, hepatocellular carcinoma 21, esophageal squamous cell carcinoma 22, and colorectal cancer." (PMID 28088836, 2017). "Interestingly, the expression of lncRNA TUG1 in lung cancer was very special." (PMID 34039257, 2021). "Similarly, knockdown of TUG1 enhanced the chemo sensitivity of lung cancer cells." (PMID 31141943, 2019). "Besides, TUG1, FAS-AS1 and THRIL expression levels were fair diagnostic markers for lung cancer." (PMID 30866866, 2019). "LncRNAs have become the key regulatory factors in development and progression of lung cancer, functioning as oncogenes (e.g., MALAT1, HOTAIR, H19 and ANRIL) or tumor suppressors (e.g., MEG3, GAS5, and TUG1)." (PMID 34976181, 2022). "In a separate study, lncRNA TUG1 was shown to elevate sensitivity to cytokines by blocking the inhibition of phosphate and tensin homolog (PTEN) through microRNA‐221 in non‐small cell lung cancer." (PMID 34766130, 2020). "The expression of BRANCR, SPRY4-IT1, AB209630, HMlinc717, TUG1, GAS6-AS1 and PANDAR was down-regulated, while the expression of other lncRNAs was up-regulated in lung cancer patients." (PMID 29137343, 2017). "In lung cancer, TUG1 was shown to be downregulated in NSCLC, and TUG1 expression was shown to be significantly lower in advanced-stage diseases and larger tumors." (PMID 27485439, 2016). "Moreover, lncRNA TUG1 exhibits dysregulated expression in COPD and lung cancer tissues, contributing to disease aggressiveness and treatment resistance." (PMID 39201688, 2024). "In our NSCLC cohort, TUG1 was downregulated in lung cancer tissues compared with the nontumor tissues." (PMID 27485439, 2016).